TCF7L2 (transcription factor 7 like 2)
Diseases named in the same sentence as TCF7L2 in open-access papers (continued):
Sharing a sentence is not in itself a finding about the gene and the disease.
hyperlipidemia (6 papers, 2015 to 2025). "In addition, the transcription factor 7-like 2 (TCF7L2) was reported to be associated with hyperlipidemia, CVD, T2D, and PCOS." (PMID 39859066, 2025). "TCF7L2 rs12255372 has also been found to be associated with high serum triglycerides and was differentially expressed in adipose tissue in families with familial combined hyperlipidaemia." (PMID 26608632, 2015). "After thorough research of the literature, only 5-6 studies could be identified which investigated the influence of TCF7L2 gene with respect to postprandial lipemia." (PMID 36263318, 2022). "Regardless, these findings implicate TCF7L2 in regulation of plasma triglyceride in the general population and in conjunction with the animal studies identify this protein as a target for drugs against hyperlipidemia." (PMID 26576435, 2015).
bladder cancer (5 papers, 2017 to 2025). "Following with the demonstrating of TCF7L2/Cofilin 1 regulating pathway in bladder cancer, we uncovered another regulating mechanism of which Cofilin 1 promoting tumor progress through miR-182-5p/Cofilin 1 regulating axis." (PMID 30858759, 2019). "In our earlier study, we reported that transcription factor TCF7L2 can binds to Cofilin 1 promoter and increases the gene expression in bladder cancer, which promotes the tumor progress." (PMID 30858759, 2019). "The results revealed that Cofilin 1, which was regulated by TCF7L2, promoted bladder cancer development." (PMID 29190896, 2017). "TCF7L2 microsatellite instability and the expression of different splice forms occur in human bladder cancer cells, suggesting that the TCF7L2-mediated signal pathway affects bladder cancer progression." (PMID 29190896, 2017). "Together, these results indicate that Cofilin 1, which is regulated by TCF7L2, promotes bladder cancer development and progression." (PMID 29190896, 2017). "Furthermore, we found that transcription factor 7-like 2 (TCF7L2) enhances Cofilin 1 expression by binding to Cofilin 1 promoter in human bladder cancer, which can promote tumor progress." (PMID 30858759, 2019). "We suspect that Cofilin 1 is regulated by TCF7L2 and affects the development of bladder cancer." (PMID 29190896, 2017). "Furthermore, we discovered that transcription factor TCF7L2 bound to the Cofilin 1 promoter to increase its expression and promote the development of bladder cancer." (PMID 29190896, 2017). "Here, we studied the effects of Cofilin 1 and TCF7L2 on bladder cancer." (PMID 29190896, 2017). "Thus, TCF7L2 contributed to Cofilin 1-induced promotion of bladder cancer development by binding to the Cofilin 1 promoter and increasing its expression." (PMID 29190896, 2017). "Together, these results suggest that TCF7L2 mediates bladder cancer progression." (PMID 29190896, 2017). "Furthermore, a recent study showed that CCDC183-AS1 is involved in bladder cancer (BC) progression via an MITF/CCDC183-AS1/miR-4731-5p/TCF7L2 signaling axis, in which TCF7L2 was identified as an essential gene in the modulation of aerobic glycolysis (the Warburg effect)." (PMID 38254754, 2024).
Hypoglycemia (5 papers, 2012 to 2019). A decreased concentration of glucose in the blood. "Surprisingly, they found the seemingly the opposite phenotype on their TCF7L2 null allele compared with our results, in that the TCF7L2 knockout mice displayed hypoglycemia that was associated with reduced plasma insulin levels." (PMID 23028378, 2012).
COVID-19 (4 papers, 2022 to 2025). A disease caused by infection with severe acute respiratory syndrome coronavirus 2. "For instance, we observed significantly stronger enrichment of TBX21 (adjusted P = 1 × 10−224), RUNX3 (adjusted P = 1 × 10−199), TCF7L2 (adjusted P = 1 × 10−167) and ZEB1 (adjusted P = 1 × 10−118) motifs in severe COVID-19 risk variant-depleted cells." (PMID 35668323, 2022). "The results of Cox analysis revealed that the RACGAP1, TCF7L2, IRF7, DMD, and JUN were significantly associated with the development of COVID-19/BRCA (p < 0.05)." (PMID 36060002, 2022). "Independent prognosis and survival analysis revealed important differential genes, including RACGAP1, TCF7L2, IRF7, DMD, and JUN, which can be used as effective biomarkers for screening and characterizing patients with BRCA and COVID-19 at all stages." (PMID 36060002, 2022).
Crohn disease (4 papers, 2009 to 2022). A gastrointestinal disorder characterized by chronic inflammation involving all layers of the intestinal wall, noncaseating granulomas affecting the intestinal wall and regional lymph nodes, and transmural fibrosis. "In Crohn’s disease, TCF7L2 gene is associated with decreased antimicrobial function of the Paneth cell where a diminished expression of TCF7L2 mediates a defective differentiation." (PMID 31089877, 2019). "TCF7L2 is critical to crypt cell proliferation and its expression is considerably decreased in the ileum of crohn's disease patients." (PMID 23593167, 2013).
esophageal cancer (4 papers, 2016 to 2025). A primary or metastatic malignant neoplasm involving the esophagus. "The expression of the TCF4/TCF7L2 protein in the nucleus of esophageal cancer cells was analyzed using immunohistochemistry." (PMID 28536608, 2016). "In this study, we found that increased expression of TCF4/TCF7L2 in the nucleus of cancer tissue cells was accompanied by the local progression of esophageal cancer." (PMID 28536608, 2016). "Although the precise molecular mechanisms through which TCF4/TCF7L2 is activated must be clarified, our data clearly indicate that TCF4/TCF7L2 may be a molecular target for the development of effective therapeutic agents for patients with esophageal cancer." (PMID 28536608, 2016). "Downstream genes of the Wnt signal pathway in esophageal cancer may be activated by TCF4/TCF7L2 activation." (PMID 28536608, 2016). "Because TCF4/TCF7L2 plays a role in cancer proliferation, additional studies are necessary to determine whether TCF4/TCF7L2 contributes to the growth of esophageal cancers." (PMID 28536608, 2016). "Therefore, our data suggest that TCF4/TCF7L2 is involved in the cell proliferation of esophageal carcinoma and that TCF4/TCF7L2 is a useful biomarker for predicting prognosis in patients with ESCC." (PMID 28536608, 2016). "To assess the influence of Wnt/β-catenin signaling in esophageal cancer cells, we first determined the expression levels of relevant Wnt-related proteins such as Axin2, active β-catenin (ABC), total β-catenin (TBC), and the Wnt-transcription factor TCF7L2 by Western blot analysis." (PMID 34638639, 2021). "Here, we investigated the clinicopathological significance of transcription factor 4/transcription factor 7-like 2 (TCF4/TCF7L2) in resectable esophageal squamous cell carcinoma (ESCC), because TCF4/TCF7L2 expression has not been studied in esophageal cancer previously." (PMID 28536608, 2016).
esophageal squamous cell carcinoma (4 papers, 2016 to 2022). Esophageal squamous cell carcinoma (ESCC) is a type of esophageal carcinoma (EC) that can affect any part of the esophagus, but is usually located in the upper or middle third. "The current study may be the first report demonstrating that TCF4/TCF7L2 is correlated with the prognosis of patients with esophageal squamous cell carcinoma." (PMID 28536608, 2016). "In this study, we aimed to examine the association of transcription factor 7-like 2, Leptin (LEP) and LEP receptor (LEPR) polymorphisms with esophageal squamous cell carcinoma (ESCC)." (PMID 29312594, 2017). "In esophageal squamous cell carcinoma, LCN2 expression is modulated by the transcription factors TCF7L2 and EGR1, leading to increased activity of matrix metalloproteinase-9 (MMP-9), rearrangement of cytoskeletal F-actin, as well as increased invasiveness and migration through the MEK/ERK pathway." (PMID 34062746, 2021).
Hyperinsulinemia (4 papers, 2018 to 2025). An increased concentration of insulin in the blood. "In fact, key metabolic features of T2D, such as hyperinsulinemia, chronic low‐grade inflammation, and impaired glucose homeostasis, may modulate the functional effects of CDKN1B and TCF7L2 variants." (PMID 40658092, 2025). "Interestingly, they have also demonstrated, both in vitro and in vivo, that hyperinsulinemia regulated the expression profile of the Wnt/β-catenin related genes positively, including the expression of Tcf7l2 in skeletal muscles." (PMID 41614817, 2025). "Interestingly, hyperinsulinemia could increase TCF7L2 mRNA expression, and subjects with low insulin sensitivity had higher TCF7L2 mRNA expression in skeletal muscle tissue." (PMID 29713286, 2018).
Intellectual disability (4 papers, 2021 to 2025). "Given strong genetic evidence that implicates Tcf7l2 in both ASD and intellectual disability and our present demonstration of its role in synaptic development, we next investigated whether astrocytic Tcf7l2 impacts social and cognitive behaviors." (PMID 37798419, 2024). "In this regard, a recent characterization of 11 patients carrying de novo loss of function mutations in TCF7L2, within or near its HMG box domain, concluded that patients often show mild intellectual disability and neuropsychiatric conditions including ASD and ADHD." (PMID 34858139, 2021).
multiple sclerosis (4 papers, 2013 to 2023). A progressive autoimmune disorder affecting the central nervous system resulting in demyelination. "TCF3 is involved in lymphocyte development, and TCF7L2 has been implicated in neural development and diseases, such as multiple sclerosis, where a role in demyelination and remyelination has been suggested." (PMID 34946971, 2021). "In demyelinating diseases, such as multiple sclerosis, TCF7L2 is reexpressed in oligodendrocytes in a subset of MS patients, but is also present in tissue samples from patients with non-demyelinating, inflammatory diseases." (PMID 23977356, 2013). "In the CNS, Tcf7l2 was identified as a critical transcription factor showing dynamic expression during the remyelination process in rodent multiple sclerosis (MS), which has been thought to result from the complex features of OL damage and failure of remyelination." (PMID 38213786, 2023).
ovarian carcinoma (4 papers, 2009 to 2020). A malignant neoplasm originating from the surface ovarian epithelium. "Although the biology of the Wnt/β-catenin signaling pathway and prior association between rs12255372 and numerous phenotypes warranted examination of this TCF7L2 SNP, no compelling evidence for association with breast or ovarian cancer was observed." (PMID 19732438, 2009).
rectal cancer (4 papers, 2019 to 2025). A primary or metastatic malignant neoplasm that affects the rectum. "In rectal cancer, the β-catenin/transcription factor 7-like 2 (TCF7L2) complex interacts with an enhancer element in the first intron of the YAP gene, inducing YAP expression and driving tumor progression." (PMID 40673277, 2025). "The Wnt transcription factor TCF7L2 is overexpressed in primary rectal cancer that is resistant to radiotherapy and chemotherapy, and TCF7L2 mediates resistance to radiotherapy and chemotherapy." (PMID 35836256, 2022).
Abdominal obesity (3 papers, 2006 to 2025). Excessive fat around the stomach and abdomen. "The T2D risk allele of rs7903146 in TCF7L2 specifically contributed to an increased risk for T2D combined with abdominal obesity (P = 3.77 × 10−2) and the T2D risk allele of rs7961581 in TSPAN8/LGR5 was related to an increased risk for T2D with elevated TG level (P = 4.61 × 10−2)." (PMID 26599349, 2015).
acute myeloid leukemia (3 papers, 2020 to 2021). Acute myeloid leukemia (AML) is a group of neoplasms arising from precursor cells committed to the myeloid cell-line differentiation. "TCF7L2 has been shown to be overexpressed in acute myeloid leukemia (AML) and represents a druggable target." (PMID 32517078, 2020). "Besides, a previous report indicated that the SIX1 can be transcriptional regulated by a transducer of WNT/β-catenin signaling, TCF7L2 in acute myelocytic leukemia, and WNT/β-catenin signaling promotes skeletal muscle development by increasing SIX1 levels (Petropoulos, Skerjanc 2002)." (PMID 32399910, 2021).
Alzheimer disease (3 papers, 2010 to 2016). A progressive, neurodegenerative disease characterized by loss of function and death of nerve cells in several areas of the brain leading to loss of cognitive function such as memory and language. "Other RBPMS partners we identified included PICALM, a clathrin adaptor with a role in Alzheimer's disease, TCF7L2, a Wnt signaling transcription factor and PATZ1, a transcriptional regulator with a role in cell death and proliferation and differentiation." (PMID 27107012, 2016).
asthma (3 papers, 2016 to 2025). "CpG cg24788483 that annotated to transcription factor 7-like 2 (TCF7L2) was reported to be related to complete remission of asthma." (PMID 34539625, 2021). "Given the expression of FZD5 and TCF7L2 in the endodermal foregut lineage cell types, we also performed SMR focusing on foregut-related tissue and phenotypes, which showed some enrichment for respiratory phenotypes including asthma." (PMID 39904980, 2025).
autoimmune disease (3 papers, 2016 to 2021). A disorder resulting from loss of function or tissue destruction of an organ or multiple organs, arising from humoral or cellular immune responses of the individual to their own tissue constituents. "SPIB, as well as E2F2, GATA4 and TCF7L2 have been associated with other autoimmune diseases through differential gene expression and genetic polymorphisms, respectively." (PMID 33915751, 2021).
chronic kidney disease (3 papers, 2014 to 2025). Impairment of the renal function secondary to chronic kidney damage persisting for three or more months. "Here we investigated the potential association of the rs7903146 polymorphism in the TCF7L2 gene with clinical profile of end-stage renal disease (ESRD) patients." (PMID 24574000, 2014). "This is in agreement with previous findings of the association of TCF7L2 genetic variants with renal function and progression of chronic kidney disease." (PMID 24574000, 2014). "The aim of our study was to investigate the potential effect of the rs7903146 (C/T) polymorphism in intron 3 of the TCF7L2 gene on clinical phenotype of end-stage renal disease." (PMID 24574000, 2014). "We described for the first time a strong relationship between the TCF7L2 gene variant rs7903146 and cardiovascular disease in end-stage renal disease patients." (PMID 24574000, 2014). "In a large, population-based study, the authors examined whether variants of TCF7L2 gene were associated with progression of chronic kidney disease and measures of kidney function." (PMID 24574000, 2014). "In the present study we investigated the potential effect of the rs7903146 (C/T) polymorphism in intron 3 of the TCF7L2 gene on clinical phenotype of diabetic and non-diabetic end-stage renal disease." (PMID 24574000, 2014). "Our findings might provide evidence showing that TCF7L2 plays an important role in the relationship between chronic kidney disease and CVD." (PMID 24574000, 2014).
developmental delay (3 papers, 2023 to 2024). "The β-catenin effector that is encoded by the TCF7L2 gene has been associated with both developmental delay and ASD through observations of multiple de novo mutations from exome sequencing analyses of large cohorts." (PMID 37798419, 2024). "To explore these data, we mapped 12 reported coding sequence mutations of TCF7L2, 10 of which were associated with developmental delay and two were associated with ASD." (PMID 37798419, 2024).
fatty liver (3 papers, 2022 to 2023). "Hepatic Tcf7l2 deficiency exacerbated liver steatosis via carbohydrate dependency owing to cell-autonomous increases in DNL." (PMID 36759348, 2023). "In mice, loss of hepatic Tcf7l2 contributes to liver steatosis by inducing preferential metabolism of carbohydrates via DNL activation." (PMID 36759348, 2023). "Pathologically, hepatic Tcf7l2 deficiency-induced fatty liver progressed to NASH, a severe form of NAFLD, demonstrating the potent effect of TCF7L2 on hepatic DNL." (PMID 36759348, 2023). "Therefore, we investigated whether TCF7L2 regulates miRs that can trigger Srebf1c mRNA decay during the development of hepatic steatosis." (PMID 36759348, 2023). "Eventually, restoring TCF7L2 expression at the physiological level in the liver of Alb-Cre;Tcf7l2f/f mice alleviated liver steatosis without altering body composition under both acute and chronic HCD conditions." (PMID 36759348, 2023). "Mice lacking hepatic Tcf7l2 displayed simple liver steatosis at 16 weeks of HCD feeding and progressive fatty liver at 34 weeks of a long-term HCD." (PMID 36759348, 2023).
heart failure (3 papers, 2016 to 2024). Inability of the heart to pump blood at an adequate rate to meet tissue metabolic requirements. "TCF7L2, also named TCF4, mediates canonic Wnt/β-Catenin signaling and c-Myc upregulation during abnormal cardiac remodeling in heart failure." (PMID 38373914, 2024). "A Link between TCF7L2, WNT/β-catenin and MYC pathways has been described during cardiac remodeling in heart failure or in the context of pancreatic beta cell proliferation." (PMID 32517078, 2020).
hypertriglyceridemia (3 papers, 2008 to 2022). A laboratory test result indicating elevated triglyceride concentration in the blood. "Alternatively, the protective effect of TCF7L2 minor variant against hypertriglyceridemia may be due to reduced adipose tissue lipolysis." (PMID 26576435, 2015). "This is the first demonstration of a significant association between TCF7L2 expression in visceral adipose tissue and PPTg dysmetabolism confirming the findings from our polymorphism studies and points to an important role of TCF7L2 gene in postprandial hypertriglyceridemia." (PMID 36263318, 2022).
intestinal tumors (3 papers, 2020 to 2023). "Further, Jun binds Tcf7l2 to cooperatively activate gene expression in Wnt-dependent intestinal tumors." (PMID 33587034, 2021). "The transcription factor TCF7L2 is indispensable for intestinal tissue homeostasis where it transmits mitogenic Wnt/β-Catenin signals in stem and progenitor cells, from which intestinal tumors arise." (PMID 32203164, 2020).
ischemic stroke (3 papers, 2009 to 2025). A stroke disorder caused by obstruction of blood flow to the brain, due to thrombotic (local blood clot formation) or embolic (due to a blood clot or other material traveling from another site) event. "To investigate the role of TCF7L2 in IS, we employed an ischemic stroke model (MCAO/R mice), and lentivirus‐packed sh‐TCF7L2 and sh‐NC were injected into MCAO/R mice brain at 24 h before‐surgery." (PMID 39822731, 2025). "TCF7L2 has shown associations with angiographically determined CHD in diabetic and non-diabetic patients, as well as with CVD, ischemic stroke, peripheral artery disease, and all-cause mortality." (PMID 24098343, 2013).
liver cancer (3 papers, 2012 to 2018). An epithelial or non-epithelial malignant neoplasm that arises from the liver. "In liver cancer cells, E2 or P4 exposure elevated TCF7L2 expression, enhanced the activity of insulin signaling (pAKT/pGSK), reduced PEPCK expression, subsequently increased insulin-stimulated glucose uptake, and decreased glucose production." (PMID 27108846, 2016).
liver fibrosis (3 papers, 2022 to 2025). "Additionally, liver fibrosis, as determined by the proportion of the Sirius red-stained area, was significantly increased upon hepatic Tcf7l2 deficiency." (PMID 36759348, 2023). "Finally, high-impact frameshift mutations in TCF7L2 (VAF = 0.133 in HCC cell line and VAF = 0.024 to 0.094 in HCC tumor regions) and CACNA1E (VAF = 0.089 in HCC tumor) were identified in the hepatic fibrosis pathway." (PMID 40340757, 2025).